RNU4-55P (RNA, U4 small nuclear 55, pseudogene)
Gene: Small nuclear RNA gene on chromosome 11 (105,824,634 to 105,824,770, forward strand). Ensembl gene ENSG00000222663.
Homologues: Orthologues: chimpanzee U4 (100% identical), macaque U4 (92% identical), tropical clawed frog U4 (56% identical), dog U4 (55% identical), rat LOC120094538 (55% identical), guinea pig U4 (54% identical), pig U4 (54% identical), tropical clawed frog U4 (54% identical), tropical clawed frog U4 (53% identical), tropical clawed frog U4 (51% identical), tropical clawed frog U4 (50% identical), tropical clawed frog U4 (48% identical). Paralogues in human: RNU4-15P (58% identical), RNU4-82P (58% identical), RNU4-39P (56% identical), RNU4-4P (56% identical), RNU4-57P (56% identical), RNU4-48P (55% identical), RNU4-91P (54% identical), RNU4-28P (53% identical), RNU4-64P (53% identical), RNU4-72P (53% identical), RNU4-22P (52% identical), RNU4-59P (52% identical), and 81 more.